RNU6-1135P (RNA, U6 small nuclear 1135, pseudogene)
Gene: Small nuclear RNA gene on chromosome 11 (87,606,783 to 87,606,885, forward strand). Ensembl gene ENSG00000223015.
Homologues: Orthologues: chimpanzee U6 (98% identical), macaque U6 (89% identical). Paralogues in human: RNU6-310P (90% identical), RNU6-477P (89% identical), RNU6-1289P (88% identical), RNU6-211P (88% identical), RNU6-1145P (87% identical), RNU6-1316P (87% identical), RNU6-1152P (86% identical), RNU6-116P (86% identical), RNU6-15P (86% identical), RNU6-166P (86% identical), RNU6-188P (86% identical), RNU6-20P (86% identical), and 1287 more.